TSC2 (TSC complex subunit 2)
Diseases named in the same sentence as TSC2 in open-access papers (continued):
Sharing a sentence is not in itself a finding about the gene and the disease.
Anxiety (16 papers, 2012 to 2025). Intense feelings of nervousness, tension, or panic often arise in response to interpersonal stresses. "Further, analysis of exploratory behavior indicated that TSC2 KO cells are sufficient to cause behavioral changes in the mice, namely anxiety-associated thigmotaxic behavior." (PMID 41255962, 2025). "This manuscript investigates the sex-specific behavioral effects of TSC2 mutation with a focus on anxiety-related, social, and learning and memory behaviors." (PMID 32303566, 2020). "Inactivating mutation in Tsc2 (Tsc2+/− mice) showed defects in axon guidance and cognitive deficits such as impaired water maze performance, and mice with Fmr1-knockout (KO) presented impairments in long-term depression, hyperactivity, anxiety-like, and unusual social behaviors." (PMID 24564913, 2014). "Like the patients, mouse models of TSC have shown varying anxiety phenotypes along a spectrum that corresponds to the Tsc2 genotype." (PMID 41255962, 2025). "On the other hand, several authors observed cognitive deficits, social impairments, and anxiety-related behaviors in the adult TSC2 animal model." (PMID 40713507, 2025). "In fact, post hoc tests for post‐KA condition, revealed that during dark phase, WT females exhibited significantly lower anxiety levels than Tsc2+/− females." (PMID 39010669, 2024). "Accordingly, here, we only found a significant increase in anxiety for Tsc2+/− females compared to their control group." (PMID 39010669, 2024). "In our previous study, curcumin, a diet-derived mTOR inhibitor has been shown to effectively mitigate learning and memory deficits and anxiety-like behavior in Tsc2+/− mice via inhibiting astroglial proliferation." (PMID 38296969, 2024). "In fact, increased anxiety paired with reduced hippocampal NAA + NAAG in Tsc2+/− females is in line with previous findings, in which NAA levels diminished in the hippocampus following fear conditioning." (PMID 35050193, 2022). "This study reveals that knockout of TSC2 in Nav1.8+ neurons increases itch- and anxiety-like behaviors and substantially modifies the distribution of adipose tissues and the metabolic responses to HFD." (PMID 36586433, 2022). "Knockout of TSC2 in Nav1.8+ neurons increases itch- and anxiety-like behaviors and substantially modifies fat storage and metabolic responses to HFD." (PMID 36586433, 2022). "Elevated anxiety was previously reported in the Tsc2+/- (Eker) rat, the findings in mouse models of TSC are contradictory." (PMID 33863288, 2021). "Possibly, the strength of anxiety-like behaviours is very low in Tsc2+/− mice, therefore, much more numerous experimental groups should be tested to confirm this phenomenon." (PMID 34576223, 2021). "In this study, we further investigated activity, anxiety-like behavior, social preference, learning and memory, and motor coordination in groups of male and female control and Tsc2 heterozygous mice." (PMID 32303566, 2020). "Moreover, previous data also support sexual dimorphism in behavior outcomes for the TSC2 mouse model, characterized by elevated anxiety levels for mutant females described as a stress‐coping strategy." (PMID 39010669, 2024). "We saw elevated anxiety in the Tsc2+/- rats only in the EPM habituation session." (PMID 33863288, 2021). "In the open field, Tsc2 mutant mice showed a trend towards less exploration of the inner sector which may also be attributed to increased anxiety." (PMID 22848848, 2012). "Additionally, in the TSC2 mouse model, in response to the proconvulsant drug, we found evidence for the involvement of the circadian cycle and biological sex in seizure occurrence and anxiety‐like behavior." (PMID 39010669, 2024). "Given that Tsc1 and Tsc2 form a complex for signal transduction and Tcs2 deletion increases anxiety, the impairment of Tsc1 mutant mice in the reversal of eyeblink conditioning is in line with our finding that an altered emotional response may limit behavioral flexibility in a mouse model of ASD." (PMID 36192805, 2022).
Anxiety (continued). "In animal models, although chronic rapamycin treatment from postnatal day 8 to 40 improved anxiety- and depression- like behaviors in a model of Tsc1, daily rapamycin administration beginning at E12.5 resulted in hippocampal-dependent learning impairment in a mice model of Tsc2." (PMID 26248290, 2015). "Indeed, dominant negative Tsc2 mutants showed increased anxiety in this test." (PMID 22848848, 2012). "Our mice behaved similarly to Tsc2-DN mice, which had decreased center exploration and traveled a similar distance in an open field; Tsc2-DN mice also spent less time in the open arms of an elevated plus maze (EPM), revealing anxiety-like behavior." (PMID 41255962, 2025). "Exploratory activity and anxiety-related behaviours were not changed in Tsc2+/− mice, as determined in the open-field test." (PMID 34576223, 2021). "We observed a weak but persistent drift toward increased anxiety in Tsc2+/− mice; however, the difference was without statistical significance." (PMID 34576223, 2021). "In a Tsc2+/− mouse model, female animals exhibited deficits in habituation response and following decreases in anxiety, suggesting that observed differences in repetitive behavior during the LSC test may arise from an impaired habituation response to the novel environment in female Tsc2+/− rats." (PMID 40611277, 2025). "All other behavioral tests assessing exploration and anxiety (light/dark box) as well as learning and memory (Pavlovian conditioned taste aversion test, Morris water maze hidden platform task including reversal learning, and probe trials) did not detect any behavioral constraints in Tsc2+/− rats." (PMID 22848848, 2012).
colorectal cancer (15 papers, 2014 to 2025). A primary or metastatic malignant neoplasm that affects the colon or rectum. "The ARID1A, BCR, CHD5, RPL22 and TSC2 genes were shared mutation targets in ovarian and colorectal carcinomas." (PMID 29296220, 2017). "Carmofur, a potent ASAH1 inhibitor that has been used to treat colorectal cancer in some countries, selectively reduced the viability of TSC2-null cells in a dose-dependent manner (IC50 = 17 μM) and to a lesser extent TSC2-addback cells (IC50 = 253 μM)." (PMID 36927688, 2023). "This was also the case for SMAD4 in pancreatic cancer, TBX3 in colorectal cancer, or TSC2 in liver cancer." (PMID 36937541, 2023). "TSC2 regulates autophagy via mTOR1 signalling in colorectal cancer and endometrial carcinoma." (PMID 34395438, 2021). "A study by Lee and colleagues showed that STK11, PRKAA1, and TSC1 polymorphisms were associated with disease-free survival after diagnosis with colorectal cancer; they did not see an association with TSC2." (PMID 25541970, 2014). "The aberrations found in this study (losses of TSC2, COL1A1, NOTCH1, MIR4673 and GNAS, and gains of MALAT1 and TALAM1) may serve as candidate biomarkers for early detection of colorectal cancer onset." (PMID 35887000, 2022). "In a previous report, we showed that gankyrin significantly enhanced the mTOR activity in colorectal cancer (CRC) through targeting TSC2 for degradation, independent of AKT signaling." (PMID 30420909, 2018).
infantile spasms (15 papers, 2017 to 2025). A rare epilepsy syndrome characterized by onset of epileptic spasms in infants between 2 and 12 months of age, and rarely up to 24 months. "Pathogenic mutations in the TSC2 gene are also linked to an increased risk of developmental disorders, intellectual disability, and infantile spasms." (PMID 37232723, 2023). "Tuber/nodule burden, early electroencephalogram characteristics in newborns and infants, infantile spasms, and TSC2 mutation have been proposed as putative early biomarkers of a pharmacorefractory course." (PMID 37946245, 2023). "The patient was initially diagnosed with West syndrome, but after a brain MRI, it appeared that bilateral, subependymal nodules were present, which confirmed the molecular diagnosis of the TSC2 variant." (PMID 36674629, 2023). "Three factors appear to significantly increase DRE risk: TSC2 mutation, infantile spasms, and a high number of cortical tubers." (PMID 34884198, 2021). "Age of onset, TSC2 mutation, and infantile spasms are independently related to DRE, as described in our article." (PMID 34884198, 2021). "Most studies observed an association between DRE and three main parameters: TSC2 mutation, infantile spasms, and the number of cortical tubers." (PMID 34884198, 2021). "Of note, Patient 4 in our cohort exhibited a missense variant in exon 30 of TSC2 and presented with infantile spasms, but had normal development." (PMID 32216820, 2020). "Patients with TSC/SIB have higher frequencies of mental retardation, TSC2 mutations, history of infantile spasms, spike focus in the left frontal lobe." (PMID 33391947, 2020). "A smaller fraction of panel-positive FCD2/HME cases (7/34) with somatic variants in MTOR, PIK3CA, or TSC2 also presented infantile spasms." (PMID 31444548, 2019). "A 9-years-old boy carrying a de novo variant of c.2197 C>G in TSC2 gene was suspected to have a clinical diagnosis of TSC at infant age because of clinical presentation of infantile spasms." (PMID 28074849, 2017). "Moreover, individuals with TSC2 mutations tend to experience an earlier onset of infantile spasms (at around 1.2 years) than those with TSC1 pathogenic variants (at around 2.7 years)." (PMID 37232723, 2023). "This suggests that, although infantile spasms can be seen in patients with central missense mutations (yet, significantly less frequently than in patients with different TSC2 pathogenic variants), developmental outcome could be favorable." (PMID 32216820, 2020). "For example, in the TOSCA study, the rate of infantile spasms was higher in TSC2 patients than in TSC1 patients (47.3% vs. 23%)." (PMID 36232477, 2022). "TSC2 pathogenic variants predict a more severe phenotype with a higher frequency of early-onset seizures, infantile spasms and developmental delay compared to patients with TSC1 or mosaic TSC2 variants." (PMID 34632383, 2021). "Furthermore, variants located in the flanking regions of the TSC2 gene, as opposed to those in its central portion (exons 22–33), have been correlated with an increased risk of infantile spasms." (PMID 40364023, 2025).
renal carcinoma (15 papers, 2012 to 2025). A carcinoma arising from the epithelium of the renal parenchyma or the renal pelvis. "Although only 10% of these heterozygous mice develop angiosarcomas and renal carcinoma, DNA analysis reveals loss of another copy of Tsc2 allele in about 30% of lesions." (PMID 29491408, 2018). "Other gene mutations, such as FANCD2, FAT3, KDM6A, KDR, TET2, and TSC2, occurred twice in this MA cohort, which was quite different from other common types of renal carcinoma." (PMID 30111351, 2018). "Initially, several studies reported that TSC2 inhibits cell proliferation in TSC2-deficient rat renal carcinoma cell lines." (PMID 23355874, 2013). "Somatic TSC2 mutation contributes to tumorigenesis, including renal cancer." (PMID 34249677, 2021). "In addition, our observation that loss of TSC2 suppressed COX2 expression through activation of mTORC1 may explain why COX2 is downregulated in renal carcinomas in the TSC2 gene mutant Eker rat." (PMID 27078846, 2016). "This locus spans the Tsc2-Pkd1 region of chromosome 17, whose candidate genes are involved in renal cancer in animal models and humans." (PMID 24148528, 2013). "Importantly, the tuberin protein product of Tsc2 expression was present in all Tsc2+/− mouse and human mesenchymal tumors, and about 80% of Tsc2+/− mouse renal carcinoma." (PMID 32365712, 2020). "There was a study that showed 5q amplification led to overexpression of the SQSTM1 oncogene in ccRCC lines and tumors, and the gene product of which, p62, regulated known renal cancer suppressor genes such as VHL, TSC1and TSC2 14,15." (PMID 31892969, 2020). "VHL, MET, folliculin (FLCN), tuberous sclerosis 1 (TSC1), TSC2, fumarate hydratase (FH) and succinate dehydrogenase (SDH) are known as renal cancer genes, and all are involved in pathways that respond to metabolic stress or nutrient stimulation." (PMID 24348776, 2014). "We next assessed the effects of HDACi on rat renal carcinoma cells named LEF2, which has a Tsc2 loss-of-function mutation, with or without re-expression of Tsc2 to suppress mTORC1 activation." (PMID 32336756, 2020). "Indeed, it has been reported that NOP56 and TSC-2 are not differentially expressed in renal carcinomas and oncocytomas (ArrayExpress: E-GEOD-12090; ArrayExpress: E-GEOD-19982), indicating loss of regulation during malignant progression." (PMID 24401680, 2014).
autosomal dominant polycystic kidney disease (14 papers, 2013 to 2025). Autosomal dominant form of polycystic kidney disease. "About 2% to 3% of patients carrying a TSC2 mutant gene will also have a grave form of autosomal dominant polycystic kidney disease caused by a deletion in a segment of the pkd1 and TSC2 genes known as contiguous gene syndrome." (PMID 23401839, 2013). "In some patients, the co-occurrence of TSC and autosomal dominant polycystic kidney disease (ADPKD) is caused by the TSC2/PKD1 contiguous gene syndrome (CGS)." (PMID 41227201, 2025). "Moreover, autosomal dominant polycystic kidney disease (ADPKD) may coexist with TSC as large deletions of TSC2 may also involve PDK1, whose mutations are responsible for ADPKD." (PMID 29378663, 2018). "The utilized TSC2 probemix contained one probe (exon 40) for the TSC2-adjacent gene, PKD1 (polycystic kidney disease 1, MIM *601313), whose mutation cause autosomal dominant polycystic kidney disease (ADPKD, MIM#173900)." (PMID 32313033, 2020). "Mutations in TSC1 or TSC2 cause the tuberous sclerosis complex (TSC), while mutations in PKD1 or PKD2 cause autosomal dominant polycystic kidney disease (ADPKD)." (PMID 26077033, 2015). "Mutations of the polycystic kidney disease type 1 (PKD1) gene, which lies adjacent to TSC2 on chromosome 16p13.3, are responsible for autosomal dominant polycystic kidney disease (ADPKD)." (PMID 39323690, 2024). "Patients with TSC2/PKD1 contiguous gene syndrome develop early-onset polycystic kidney lesions, which tend to grow more rapidly than those in classical autosomal dominant polycystic kidney disease." (PMID 39323690, 2024). "The TSC2 gene lies immediately adjacent to PKD1 (OMIM #601313), which encodes polycystin-1 and is the major gene causing autosomal dominant polycystic kidney disease (ADPKD, MIM#173900)." (PMID 32695431, 2020). "Furthermore, TSC2 lies directly adjacent to PKD1, the gene responsible for autosomal dominant polycystic kidney disease (ADPKD), and TSC patients can have large genetic deletions that span both genes in a disorder known as TSC2/PKD1 contiguous gene syndrome." (PMID 38802873, 2024).
cardiac rhabdomyoma (14 papers, 2019 to 2025). A well circumscribed benign tumor arising from cardiac muscle. "TSC results from mutations in TSC1 or TSC2 genes and leads to benign tumor formation in various organs, including cardiac rhabdomyomas and CNS lesions like cortical tubers." (PMID 40427120, 2025). "Mutations in TSC1/TSC2 genes are often associated with cardiac rhabdomyomas in TSC." (PMID 38534508, 2024). "The prevalence of DD/ID, renal AML, retinal hamartoma, and cardiac rhabdomyoma was significantly higher in TSC2 than in TSC1 patients." (PMID 36232477, 2022). "Furthermore, SEGA, cardiac rhabdomyomas, and renal AML occurred more frequently in patients with TSC2 variants than patients with TSC1 variants." (PMID 37946245, 2023). "Moreover, cardiac rhabdomyomas were more common in TSC2, and ungual fibroma (UF) was more common in TSC1 patients." (PMID 36232477, 2022). "In this article, we report a case of fetal cardiac rhabdomyoma due to paternal mosaicism in TSC2." (PMID 32871942, 2020). "When fetal cardiac rhabdomyoma is identified via prenatal ultrasound, TSC1/TSC2 gene testing should be incorporated into routine evaluations to differentiate hereditary TSC from sporadic cardiac tumors." (PMID 41142004, 2025). "When cardiac rhabdomyoma is suggested by ultrasound, TSC1/TSC2 gene testing (e.g., whole-exome sequencing or targeted gene panels) is recommended, irrespective of family history." (PMID 41142004, 2025). "The diameter of the largest cardiac rhabdomyoma in TSC1 and TSC2 patients was also investigated and ranged from 5 mm up to 34 mm, with the majority (22%) ranging from 10 to 15mm." (PMID 35440050, 2022). "Cardiac rhabdomyomas were also found in TSC1 patients, but were approximately twice as common in TSC2 patients." (PMID 36232477, 2022). "The prevalence of UF and cardiac rhabdomyoma was higher in TSC1 and TSC2 patients, respectively." (PMID 36232477, 2022).